PCA3 (prostate cancer associated 3)
Synonyms: DD3; NCRNA00019; PCAT3; PRUNE2-AS1
Gene: Long non-coding RNA gene on chromosome 9 (76,691,980 to 76,863,307, forward strand). Ensembl gene ENSG00000225937.
Diseases named in the same sentence as PCA3 in open-access papers:
PCA3 is named in the same sentence as 41 diseases in open-access papers, as found by Europe PMC text mining. Sharing a sentence is not in itself a finding about the gene and the disease. The quoted sentences say what the papers report.
prostate carcinoma (312 papers, 2007 to 2025). A carcinoma that arises from epithelial cells of the prostate gland. "PCA3, for instance, is widely known for its association with prostate cancer, where it serves as a biomarker for cancer detection and progression." (PMID 40584439, 2025). "Other work identified nearly 8000 cancer-specific lncRNAs, including PCA3 for prostate cancer, emphasizing their diagnostic and prognostic potential." (PMID 40861865, 2025). "For example, in previous reports, although PCA3 has been approved as a PCa diagnostic marker, it has certain limitations, such as low sensitivity in patients with low-grade prostate cancer." (PMID 40243658, 2025). "For example, in lung cancer, miRNA panels derived from liquid biopsies can differentiate benign from malignant lesions, while in prostate cancer, lncRNAs such as PCA3 have been established as clinical diagnostic markers." (PMID 41357241, 2025). "In prostate cancer, two different exosome biomarkers, prostate cancer-associated 3 (PCA-3) and transmembrane serine protease 2 (TMPRSS2), are directly associated with incidence." (PMID 38693223, 2024). "For instance, lncRNA prostate cancer antigen 3 (PCA3) has been established as a non-invasive initial diagnostic indicator for prostate cancer, demonstrating reliable test characteristics and clinical utility (NCT01632930)." (PMID 39267831, 2024). "The top three overexpressed genes whose differential expression was associated with prostate cancer are PCA3, SPINK1, and AMACR, which encode prostate cancer antigen 3, serine protease inhibitor Kazal-type 1, alpha-methylacyl-CoA racemase." (PMID 38173042, 2024). "Liquid biopsy advancements enable the detection of lncRNAs in blood or urine, exemplified by urine PCA3 as a prostate cancer diagnostic marker." (PMID 38226979, 2024). "In 2012, the FDA approved a diagnostic test for prostate cancer based on the detection of the elevated expression of lncRNA PCA3 in urine." (PMID 38790894, 2024). "PCA3 (Prostate Cancer Associated 3) was a potentially useful feature in both fractions, albeit tentatively in the EV fraction." (PMID 36765747, 2023). "Some lncRNAs are already approved by the FDA for diagnostic biomarkers, which is the case for PCA3 lncRNA in prostate cancer." (PMID 37958880, 2023). "EVs isolated from the urine of prostate cancer patients have shown the presence of prostate cancer biomarkers, PCA-3 and TMPRSS2:ERG thus showing specific diagnostic and clinical value for the transcriptome within tumor EV." (PMID 37091854, 2023). "PCA3 is an example of oncogenic lncRNAs that has been approved as a diagnostic marker in prostate cancer." (PMID 37025585, 2023). "The PCA3 gene has been detected in 95% of prostate cancer samples, making it highly associated with the disease." (PMID 37754118, 2023). "The PCA3 is a urine test that measures the expression of the prostate cancer gene 3 (PCA3) to assess prostate cancer risk and therefore reduce the number of unnecessary biopsies." (PMID 37373928, 2023). "Prostate cancer gene 3 (PCA3) is specifically expressed in the prostate and is strongly associated with prostate cancer." (PMID 37754118, 2023). "This study thus evaluated the diagnostic and prognostic potential of urinary PCA3 as an alternative biomarker for prostate cancer in the Ghanaian population." (PMID 36246565, 2022). "To predict the accuracy for predicting the accuracy for detecting prostate cancer, we report that PCA3 had an AUC of 83.0 compared to 59.5 for serum PSA, with urine PCA3 showing significant association with prostate cancer detection." (PMID 36246565, 2022). "Receiver operating characteristic curve (ROC) analysis was used to evaluate the diagnostic accuracies of serum PSA, DRE, and PCA3 as diagnostic tools for prostate cancer." (PMID 36246565, 2022).
prostate carcinoma (continued). "For example, lncRNA prostate cancer-associated 3 (PCA3) is used in the diagnosis of prostate cancer, and highly upregulated in liver cancer (HULC) is meaningful to the diagnosis of liver cancer and the identification of hepatic metastasis in colorectal cancer." (PMID 36389111, 2022). "lncRNA PCA3 in urine samples has received the approval of the FDA as a diagnostic molecule for prostate cancer." (PMID 34527584, 2021). "This study provided us with a better understanding of processes associated with the aptamer/PCA3 interaction, which is a significant step toward the development of a simple, cost-effective, and reliable methodology for the early diagnosis of prostate cancer." (PMID 34884504, 2021). "Here, we review the role of tumor markers of toxicity and response to radiation therapy in patients with prostate cancer, including prostate specific antigen, human kallikrein 2, osteopontin, prostate cancer associated 3, citrulline, and others." (PMID 33490732, 2021). "For example, prostate-specific lncRNA prostate cancer antigen 3 (PCA3) levels have been suggested as a diagnostic biomarker of prostate cancer." (PMID 34179148, 2021). "Increased expression of PCA3 increases the proliferative, invasive, and migratory ability of prostate cancer cells and it is currently used as a diagnostic tool in managing prostate cancer." (PMID 34204445, 2021). "A noncoding mRNA, the prostate cancer antigen (PCA3) complements the PCA to aid clinicians in decision-making, with a PCA3 score of 25 or higher associated to a risk of finding prostate cancer on subsequent biopsy." (PMID 34778890, 2021). "Markers selected for the model include well-known genes associated with prostate cancer and proven in other diagnostic tests, such as PCA3, HOXC6, and the TMPRSS2/ERG gene fusion." (PMID 33925381, 2021). "has determined the diagnostic value of PCA3 for the detection of prostate cancer, with sensitivity and specificity of 62% and 75%, respectively." (PMID 34527584, 2021). "For example, SAL-RNAs was classified as Senescence-associated lncRNAs, and PCA3/PCAT1 as Prostate cancer-associated transcripts (PCATs)." (PMID 33240586, 2020). "Well-known prostate cancer-associated genes such as PCA3, TMPRSS2, and CST3 were found to be upregulated in urinary sediment RNA from the higher-risk cancer group compared to those lower-risk group." (PMID 33363151, 2020). "Prostate cancer antigen 3 (PCA3), an early diagnostic biomarker for prostate cancer (PCa), is the first and only approved lncRNA for clinical use at this time." (PMID 33330574, 2020). "A PCA3 score <25 is associated with a decreased chance of prostate cancer on subsequent repeat biopsy." (PMID 31013716, 2019). "They found %p2PSA (AUC = 0.68), PHI (AUC = 0.71) and PCA3 (AUC = 0.66) can give a good diagnostic ability for prostate cancer." (PMID 31313500, 2019). "Concerning the potential role of lncRNAs as diagnostic biomarkers, the most inspiring example is PCA3 (Prostate Cancer Antigen 3) for prostate cancer diagnosis." (PMID 31653018, 2019). "Experimental studies have highlighted lncRNAs as potential biomarkers for prognoses and treatments in patients with different types of cancer, including prostate cancer, where the PCA3 lncRNA is currently used as a diagnostic tool and management strategy." (PMID 29755696, 2018). "PCAT3, also known as PCA3, is one of the most specific prostate cancer diagnostic biomarker involved in controlling prostate cancer cell surviving and modulating androgen receptor signaling." (PMID 29552304, 2018). "Logistic regression analysis of associations between PCA3 variant genotype and prostate cancer risk." (PMID 29412547, 2018). "Our aim of the current study was to re-validate the effect of PCA3 polymorphism on prostate cancer risk in an Eastern Chinese population and then estimate possible genetic discrepancies among population." (PMID 29412547, 2018).
prostate carcinoma (continued). "The association of prostate cancer risk with PCA3 polymorphism -845G>A was mainly determined in the present study, and also was firstly evaluated in an Eastern Chinese population." (PMID 29412547, 2018). "The STR TAAAn repeat in the promoter region of the lncRNA PCA3 (prostate cancer gene antigen) has been found as a risk factor for prostate cancer." (PMID 29351317, 2018). "Stratification analysis for associations between PCA3 variant and prostate cancer risk by dominant genetic model in all subjects of Eastern chinese man." (PMID 29412547, 2018). "For example, PCA3, a prostate-specific lncRNA notably overexpressed in prostate cancer, has been developed into diagnostic assay to detect prostate cancer." (PMID 28738846, 2017). "For example, the Prostate Cancer Associated gene 3 (PCA3) lncRNA is highly expressed in prostate cancer and can be detected in the urine of patients with prostate cancer." (PMID 28423633, 2017). "Since the claim is that “DD3 is one of the most prostate cancer-specific genes yet described”, testing PCA3 level in variants clinical specimens including blood, urine, ejaculate, and other body fluid was sequentially proposed and clinically conducted." (PMID 28938580, 2017). "A TG dinucleotide repeat in PCA3 was significantly associated with prostate cancer risk and aggressiveness in our analysis of over 2,000 prostate cancer patients and controls." (PMID 29203868, 2017). "In prostate cancer, the up-regulated prostate cancer antigen 3 (PCA3; also known as DD3), is already available as a diagnostic test in urine." (PMID 28915709, 2017). "Another notable example is PCA3, a prostate-specific lncRNA which has been used as a biomarker leading to the development of a clinical PCA3 diagnostic assay for prostate cancer diagnosis." (PMID 28978906, 2017). "The association between PCA3 score and aggressive prostate cancer needs further evaluation in controlled studies to confirm the utility in selecting men with clinically insignificant prostate cancer." (PMID 26628213, 2015). "The altered gene expression in these adjunct tests can elucidate changes in the biology of prostate cancer, such as PCA3, which is associated with prostate cancer-cell survival and androgen receptor signaling." (PMID 26473288, 2015). "PCA3, which has been measured in urine in men at risk of prostate cancer, is over-expressed in prostate cancer cells compared with benign prostatic tissues." (PMID 26628213, 2015). "Genes typically associated with prostate cancer are evident: PCA3 and GDF15 levels are elevated, and TP63 and MSMB levels are reduced across all tumour subgroups, and are not subtype-specific." (PMID 26501111, 2015). "For example, differential methylation of Sept9 in patient blood is used for diagnosis of colorectal cancer and detection of the non-coding RNA PCA3 in patient urine is used for risk assessment of prostate cancer." (PMID 25472429, 2014). "For example, the lncRNA prostate cancer gene 3 (PCA3) is highly associated with prostate cancer and is routinely used to indicate prostate cancer risk from urine samples." (PMID 24627686, 2014). "One of the lncRNA utilized in a clinical test is prostate cancer associated (PCA3), which is a prostate cancer specific lncRNA." (PMID 24294175, 2013). "Based on the development of the clinical urine test and incorporation into many prostate cancer risk calculations, PCA3 is likely to become a lead biomarker." (PMID 22641253, 2012). "The prostate cancer gene 3 (PCA3) test, a urinary diagnostic test for prostate cancer, uses a first-catch urine sample collected after a brief prostate massage (post-massage sample)." (PMID 20648010, 2010). "The overexpression of PCA3 has been associated with the pathogenesis of prostate cancer." (PMID 40672393, 2025). "The results suggest that PCA3 may be a useful marker to support therapeutic decisions, especially in patients with intermediate- and high-risk of prostate cancer." (PMID 41374944, 2025).
prostate carcinoma (continued). "However, a major advancement is the discovery that the prostate cancer antigen 3 (PCA3) can be used as a diagnostic marker for prostate cancer (PCa) that currently has received approval for clinical use." (PMID 39553554, 2024). "For instance, the lncRNA PCA3 (Prostate Cancer Antigen 3) is used as a diagnostic marker for prostate cancer, and it can be easily found in urine samples; the lncRNA HOTAIR (HOX antisense intergenic RNA) is involved in hormone therapies resistant in breast cancer." (PMID 38095719, 2024). "For instance, highly upregulated lncRNA in liver cancer (HULC), is significant for the diagnosis of liver cancer and the identification of hepatic metastasis in colorectal cancer, and lncRNA prostate cancer-associated 3 (PCA3) is used in the diagnosis of prostate cancer." (PMID 38132192, 2023). "The FDA has approved the first lncRNA-based diagnostic test, PCA3 ProgensaTM, for prostate cancer." (PMID 37670949, 2023). "Similarly, the diagnostic lncRNA biomarker, PCA3, has been approved for clinical use in suspected cases of prostate cancer." (PMID 36010859, 2022). "Notably, PCA3 is promising as a more efficiency diagnostic biomarker for prostate cancer than the currently used prostate-specific antigen." (PMID 36289466, 2022). "However, so far only one ncRNA, Prostate Cancer Associated 3 (PCA3) is used in clinical settings as a biomarker for prostate cancer." (PMID 36685879, 2022). "Previous reports demonstrated that PCA3 was present in urine and could be a diagnostic marker for prostate cancer." (PMID 34439239, 2021). "Similarly, the levels of the long non-coding RNA prostate cancer associated 3 (PCA3) were abundantly found in urine of patients with prostate cancer, constituting a promising non-invasive biomarker for the diagnosis of that cancer." (PMID 32183400, 2020). "PCA3 (Prostate cancer associated 3) is strongly upregulated in prostate cancer." (PMID 30567492, 2018). "Another study showed that knockdown of PCA3 sensitized prostate cancer cells to Enzalutamide, thus PCA3 may act as both a potential diagnostic and therapeutic biomarker." (PMID 30200254, 2018). "Therefore, further studying PCA3 polymorphism which can alter its expression and then alter its function provide clues for the clini-cal management of prostate cancer." (PMID 29412547, 2018). "Notably, a TAAA STR in the PCA3 promoter was recently found to correlate with prostate cancer risk in Chinese men32." (PMID 29203868, 2017). "Although the study of PCa biomarkers has been primarily focused on the lncRNA PCA3, a variety of other lncRNAs have been identified as being associated to prostate cancer development and progression, which may serve as potential biomarkers." (PMID 28272371, 2017). "Moreover, platelets isolated from patients with glioma and prostate cancer contained the cancer-associated RNA biomarkers EGFRvIII and prostate cancer antigen 3 (PCA3), respectively." (PMID 26544515, 2016). "We have demonstrated that tumor cells transfer (mutant) RNA into blood platelets in vitro and in vivo, and showed that blood platelets isolated from glioma and prostate cancer patients contain the cancer-associated RNA biomarkers EGFRvIII and PCA3, respectively." (PMID 27444431, 2016). "lncRNAs are detectable in bodily fluids and may thereby serve for cancer diagnosis: The PROGENSA® PCA3 Assay utilizes the detection of the lncRNA PCA3 in urine as diagnostic biomarker for prostate cancer." (PMID 25685243, 2015). "Additionally, polymorphisms of another long noncoding RNA, PCA3, were associated with the risk of prostate cancer." (PMID 26110379, 2015). "Also, more recent studies confirm this result with high diagnostic accuracy (equal to 86.8%) of PCA3 score cut-off >20 in the presence of a microfocus of significant prostate cancer." (PMID 27351008, 2014).
prostate carcinoma (continued). "Considering the heterogeneous nature of bacterial and nonbacterial prostate inflammation and the recurrence rates, chronic inflammation of the prostate may have an effect on the diagnostic accuracy of urinary PCA3 and may impact the accuracy of urinary PCA3 in predicting prostate cancer." (PMID 36246565, 2022). "However, scanty or no clinical data is currently available on the potential of the prostate cancer gene 3 (PCA3) urine assay as a screening and/or diagnostic tool in other population especially in the African population where the incidence of prostate cancer is on the rise." (PMID 36246565, 2022). "However, proof of concepts for the meaningful use of lncRNAs present in body fluids has been obtained with the characterization of urinary PCA3 levels as a diagnostic tool in prostate cancer, and circulating LIPCAR levels for prognosis after myocardial infarction." (PMID 26992233, 2016). "Similarly, PCGEM1, PCA3 or PRNCR1 are three lncRNAs exclusively associated with prostate cancer." (PMID 23887658, 2013). "The PCA1 cluster exhibited higher CRPC-AR module score compared to PCA2 and PCA3 clusters, suggesting its classification as an AR-positive prostate cancer (ARPC) subtype." (PMID 39743630, 2025). "Urinary mRNAs, including those of PSMA, PCA3, and AR, play a significant role in prostate cancer development." (PMID 39859417, 2025). "Together, PSMA, PCA3, and AR, which play pivotal roles in prostate cancer development, represent key aspects of tumor biology, such as cancer progression and androgen-dependent growth." (PMID 39859417, 2025). "For example, the lncRNA PCA3, specific to prostate cancer, can be detected in urine, providing a non-invasive diagnostic tool." (PMID 40861865, 2025). "PCA3 is prostate-specific and is detected in varying amounts in localized and generalized forms of prostate cancer." (PMID 40115018, 2025). "PCA3 is a non-coding RNA overexpressed in prostate cancer approved by the Food and Drug Administration (FDA)." (PMID 40868988, 2025). "PCA3, a long non-coding RNA (lncRNA), is highly expressed specifically in prostate cancer and has been used for urine detection of prostate cancer." (PMID 39988626, 2025). "For this reason, this fusion gene has become another potential biomarker used for the diagnosis of prostate cancer, not only as a single parameter but also in combination with others, such as PCA3." (PMID 40115018, 2025). "For example, lncRNA PC antigen-3 (PCA-3), approved by the FDA in 2012 as the PROGENSA PCA-3 assay, serves as a urine-based marker for Prostate Cancer (PC) by measuring the ratio of PCA3 to prostate-specific antigen (PSA) levels." (PMID 40703556, 2025). "PCA3 is a non-coding RNA highly specific to the prostate gland and markedly overexpressed in prostate cancer cells." (PMID 41374944, 2025). "By analyzing the expression profiles of RNA biomarkers such as ERG, PCA3, and SPDEF in exosomes, this technology can effectively distinguish high-risk prostate cancer (Gleason score ≥ 7) from low-risk cases." (PMID 40277513, 2025). "PCA3 is a particular lncRNA for the detection of prostate cancer in a urine test approved by the FDA." (PMID 40356687, 2025). "For example, urine lncRNA PCA3 is already a biomarker for early prostate cancer, with test strips being tested in clinical trials." (PMID 39252325, 2024). "Due to its easy availability in non-invasive samples (urine), PCA3 has become an attractive biomarker for the non-invasive early detection of prostate cancer." (PMID 39589993, 2024). "PCA3 is a well-known overexpressed gene in prostate cancer and has been identified as a possible candidate as an early detection biomarker." (PMID 38173042, 2024). "In prostate cancer, genome-wide RNA-Seq analysis identified many lncRNAs that are up- or down-regulated in prostate cancer, such as PCA3, PCGEM1, and PCAT-1 are highly associated with prostate cancer." (PMID 39403375, 2024).